SYN2 (synapsin II)
Description:
Neuronal phosphoprotein that coats synaptic vesicles, binds to the cytoskeleton, and is believed to function in the regulation of neurotransmitter release. May play a role in noradrenaline secretion by sympathetic neurons (By similarity).
Synonyms: SYNII; SYNIIa; SYNIIb
Tractability: Antibody: its Gene Ontology location is reachable by antibodies, with medium confidence. PROTAC: ubiquitination databases record sites on it; its protein half-life has been measured.
Gene: Protein-coding gene on chromosome 3 (12,004,388 to 12,192,032, forward strand). Ensembl gene ENSG00000157152.
Subcellular location: Synapse
Subcellular location (Human Protein Atlas): Nucleoplasm
Pathways (Reactome):
Neuronal System: Dopamine Neurotransmitter Release Cycle; Serotonin Neurotransmitter Release Cycle
Gene Ontology:
Molecular function: protein binding; ATP binding; identical protein binding
Biological process: chemical synaptic transmission; neurotransmitter secretion; synapse organization; synaptic vesicle clustering; calcium-ion regulated exocytosis; synaptic vesicle cycle
Cellular component: synapse; synaptic vesicle membrane; glutamatergic synapse; plasma membrane; postsynaptic density; Schaffer collateral - CA1 synapse; SNARE complex; synaptic vesicle
Genetic constraint (gnomAD): Loss-of-function variants: 16 observed, 45.11 expected, observed/expected ratio (o/e) 0.35, 90% interval 0.24 to 0.54. The upper end of that interval is the gene's LOEUF score, 0.54, which puts it in group 2 of 6, group 1 being the genes least tolerant of losing a copy. Missense variants: 473 observed, 510.96 expected, observed/expected ratio (o/e) 0.93, 90% interval 0.86 to 1. Synonymous variants: 195 observed, 196.36 expected, observed/expected ratio (o/e) 0.99, 90% interval 0.88 to 1.12.
Homologues: Orthologues: macaque SYN2 (99% identical), chimpanzee SYN2 (98% identical), dog SYN2 (96% identical), mouse Syn2 (95% identical), rat Syn2 (95% identical), pig SYN2 (78% identical), guinea pig SYN2 (76% identical), tropical clawed frog syn2 (64% identical), zebrafish syn2a (52% identical). Paralogues in human: SYN1 (63% identical), SYN3 (59% identical).
Diseases named in the same sentence as SYN2 in open-access papers:
SYN2 is named in the same sentence as 52 diseases in open-access papers, as found by Europe PMC text mining. Sharing a sentence is not in itself a finding about the gene and the disease. The quoted sentences say what the papers report.
epilepsy (18 papers, 2012 to 2024). A brain disorder characterized by episodes of abnormally increased neuronal discharge resulting in transient episodes of sensory or motor neurological dysfunction, or psychic dysfunction. "Large-scale search for genetic susceptibility loci in epilepsy identified SYN2 as one of the five major genes that contribute to epilepsy predisposition in humans." (PMID 37947886, 2023). "The evidence for an association between rare variants in SYN2 and epilepsy remains weak as the missense variants carried by the single described case has subsequently been reported in gnomAD." (PMID 36568968, 2022). "Synapsin deficiency can cause epilepsy in humans, and synapsin II (SynII) in knockout (KO) mice causes generalized epileptic seizures." (PMID 35326282, 2022). "Early suggestions of an association between epilepsy and a common intron variant in SYN2 have become less compelling in larger genome-wide association studies (International League Against Epilepsy Consortium on Complex, 2018)." (PMID 36568968, 2022). "SYN2 has been implicated previously in epilepsy, since certain genetic variants of this protein contribute to the predisposition to epilepsy and its differential effect on inhibitory and excitatory synapses." (PMID 29634780, 2018). "Nonsense and missense mutations in SYN1/SYN2 genes have been identified as causative for epilepsy and autism spectrum disorder (ASD) in humans." (PMID 29721159, 2018). "Mutations in the SYN1 and SYN2 genes are associated with epilepsy and/or ASD and the identification of the pathogenic mechanisms leading to the overt clinical manifestations is fundamental to establish personalized therapies." (PMID 29163811, 2017). "SYN2 was found among the five neural genes whose single nucleotide polymorphisms (SNPs) contribute to epilepsy predisposition in a screening of 279 prime candidate genes in 2717 cases of epilepsy." (PMID 23956174, 2014). "Genetic mapping analysis identified SYN2 among a restricted number of genes significantly contributing to epilepsy predisposition." (PMID 24009558, 2013). "Finally, a large-scale search for genetic susceptibility loci in epilepsy identified Syn2 as one of the five major genes that contribute to epilepsy predisposition." (PMID 35326282, 2022). "In addition, multicenter gene mapping analysis identified SYN2 as one of the main genes contributing to epilepsy predisposition." (PMID 29721159, 2018). "SYN2 alterations in humans seem to confer predisposition for epilepsy." (PMID 24009558, 2013). "Indeed, knockout experiments have shown the absence of SYN2 to induce epileptic-like seizures in mice and genetic mapping identified variants in the SYN2 gene as significantly contributing to epilepsy predisposition." (PMID 22384280, 2012). "In contrast, AAC2 treatment promoted the expression of inhibitory synaptic genes, Syn2 (synapsin II) and Syp (synaptophysin), examined in the context of vesicular trafficking of neurotransmitters, and mutation (T198I) is associated with epilepsy and intellectual disability." (PMID 39519239, 2024). "Interestingly, several loss-of-function mutations in SYN1 and SYN2 genes have been identified in patients suffering of epilepsy and/or autism spectrum disorders (ASD) and SYN2 has been identified as one of the highest risk epilepsy genes in a wide screen population." (PMID 29163811, 2017). "Here, we investigated possible epileptogenic abnormalities in the function of the DG neuronal network in the Synapsin II (Syn II) knockout mouse (Syn II−/−), a genetic mouse model of epilepsy." (PMID 24009558, 2013). "Moreover, several studies of single and multiple Syn KO mice models confirmed the relationship between the Syn1/Syn2 genes, epilepsy, and autism." (PMID 36409372, 2022). "DNAJC5, FRRS1L, SHANK3, SYN1, and SYN2 were epilepsy-related genes." (PMID 33584793, 2020).
epilepsy (continued). "Mutations in SYN1 were mainly identified in patients affected by both epilepsy and autism, whereas, mutations in SYN2 were observed in cases of ASD without association with epilepsy." (PMID 25237665, 2014). "By screening a cohort of ASD individuals affected by ASD and/or epilepsy for SYN genes other than SYN1, we have identified several rare variants in SYN2, namely one nonsense (n = 1) and two missense (n = 2) mutations in ASD patients and one missense (n = 1) mutation in an epileptic patient." (PMID 23956174, 2014). "Based on these observations, we hypothesized that mutations in SYN2, similarly to mutations in its functionally related gene SYN1, can predispose to ASD or epilepsy." (PMID 23956174, 2014). "To further investigate the timing of initiation of physical activity and epileptogenesis, we also studied epilepsy-prone genetically modified mice lacking synapsin II (SynIIKO), a model of focal epilepsy with secondary generalization." (PMID 31844999, 2019). "Experimentally, we also determined how physical activity could affect the development of epilepsy in epilepsy-prone synapsin II knockout mice (SynIIKO), with and without free access to a running wheel." (PMID 31844999, 2019).
schizophrenia (14 papers, 2005 to 2023). A major psychotic disorder characterized by abnormalities in the perception or expression of reality. "SYN2 has been previously linked with bipolar disorder and in GWAS with schizophrenia, whereas PPARG has also been linked to bipolar disorder and schizophrenia in other research." (PMID 32381021, 2020). "Genetic association studies have linked SYN2 to epilepsy and schizophrenia, while brain expression studies have shown significant dysregulation in alcoholism, Huntington’s disease, schizophrenia and bipolar disorder." (PMID 27515700, 2016). "Genetic association studies have also linked SYN2 variants with schizophrenia, as shown in affected families of different genetic backgrounds." (PMID 22384280, 2012). "Even after the Bonferroni correction (number of haplotypes, n = 21), the associations of the SYN2-1 – SYN2-2 and SYN2-2 – SYN2-4 haplotypes with schizophrenia remained significant (Pcorr = 9.35 × 10-5 and Pcorr = 0.019)." (PMID 16131404, 2005). "The three-way haplotype (SYN2-1, SYN2-2, and SYN2-4) also showed a significant association with schizophrenia (Pcorr = 1.1 × 10-5)." (PMID 16131404, 2005). "The three-way haplotype analyses also revealed a significant association of SYN2 with schizophrenia (P < 0.001 after Bonferroni correction)." (PMID 16131404, 2005). "The T allele-the deletion allele haplotype for the SYN2-1 – SYN2-2 combination and the deletion allele-the G allele haplotype for the SYN2-2 – SYN2-4 combination were observed more frequently in schizophrenia than the controls." (PMID 16131404, 2005). "We also investigated the association of three-way haplotypes formed by SYN2-1, SYN2-2, and SYN2-4 with schizophrenia." (PMID 16131404, 2005). "Since two independent studies have reported a significant haplotype association of SYN2 with schizophrenia, this gene is probably involved in the pathogenesis of schizophrenia." (PMID 16131404, 2005). "Interestingly, many of the up-regulated genes are involved in mental conditions and higher cognitive functions, including the schizophrenia- and autism-associated gene SYN2 and cognition- and intelligence-associated genes FMN2, CTNND2, and CACNA1A 67–71." (PMID 36788214, 2023). "Moreover, a positive association between schizophrenia and variants of the SYN2 gene, such as SNPs and insertion/deletion polymorphisms, has been observed in Chinese subjects, in the Korean population and in northern European families." (PMID 23956174, 2014). "In this study, we observed significant, pairwise haplotype associations with schizophrenia for two pairs of SNPs in SYN2 (SYN2-1 – SYN2-2 and SYN2-2 – SYN2-4; Pcorr = 9.35 × 10-5 and Pcorr = 0.019, respectively) and one pair of SNPs in CPLX2 (CPLX2-1 – CPLX2-2, Pcorr = 0.009)." (PMID 16131404, 2005). "In addition, the haplotype constructed from three polymorphisms (SYN2-1, SYN2-2, and SYN2-4) showed a significant association with schizophrenia." (PMID 16131404, 2005). "Three studies measured synapsin protein levels, and one found a significant reduction in synapsin III, while of the two studies quantifying mRNA, one found a significant reduction in synapsin II in schizophrenia." (PMID 29511299, 2019). "Additional work has been reported for SYN2 at the protein or mRNA levels, where several studies showed significant dysregulation in alcoholism, Huntington's disease, and schizophrenia." (PMID 22384280, 2012). "Seven genes, APP, ERBB3, FEZ1, HSPA2, SERPINI1, SOX10 and SYN2, display altered expression in studies of schizophrenia or bipolar disorder." (PMID 19300510, 2009). "Genotype distributions and allele frequencies of each polymorphism of the SYN2 and CPLX2 in the schizophrenia and control groups." (PMID 16131404, 2005). "For the combination of SYN2-1, SYN2-2, and SYN2-4, the estimated frequencies of the T-deletion-G haplotype differed between the schizophrenia (0.570) and controls groups (0.440)." (PMID 16131404, 2005).
schizophrenia (continued). "In this report, we present an association study of SYN2 and CPLX2 with schizophrenia using 12 polymorphisms in the Korean population." (PMID 16131404, 2005). "We found significant differences in the haplotype frequencies in both SYN2 and CPLX2 polymorphisms between schizophrenia and control groups." (PMID 16131404, 2005). "Based on their localization, well-established neurobiological roles, and expression patterns in schizophrenic patients, we selected SYN2 and CPLX2 as candidate genes for conferring susceptibility to schizophrenia." (PMID 16131404, 2005). "Our results suggest that both SYN2 and CPLX2 polymorphisms may contribute susceptibility to schizophrenia in the Korean population." (PMID 16131404, 2005). "Six single nucleotide polymorphisms (SNPs) and one 5-bp insertion/deletion in SYN2 and five SNPs in CPLX2 were genotyped in 154 Korean patients with schizophrenia and 133 control patients using direct sequencing or restriction fragment length polymorphism analysis." (PMID 16131404, 2005). "Previous studies have reported that the protein and mRNA levels of the synapsin 2 (SYN2) and complexin 2 (CPLX2) genes were decreased in patients with schizophrenia." (PMID 16131404, 2005).
autism (7 papers, 2013 to 2023). Persistent deficits in social interaction and communication and interaction as well as a markedly restricted repertoire of activity and interest as well as repetitive patterns of behavior. "Interestingly, Syn2-/- mice also exhibit an autism-related phenotype with cognitive and social impairment during the epileptogenesis phase at 2 months as well as in the tonic-clonic phase." (PMID 26177381, 2015). "Hence, in addition to SYN1, also SYN2 can participate in the ‘synaptic autism pathway’, implicating the whole Syn family of synaptic genes essential for activity-dependent changes in neuronal function in the pathogenesis of ASD." (PMID 23956174, 2014).
Cognitive impairment (4 papers, 2017 to 2022). Abnormal cognition is characterized by deficits in thinking, reasoning, or remembering. "Besides, the reduction of SYN2 was also thought to disrupt the release of neurotransmitters, which caused synaptic dysfunction and cognitive deficits." (PMID 34689137, 2021). "Taken together, our finding indicated that loganin prevented cognitive impairment related with the increased expression of SYN2 and Cplx2 that were involved in the regulation of synaptic dysfunction." (PMID 34689137, 2021). "It had been reported that the lowering expression of SYN2 induced by oligomeric α-synuclein exacerbated cognitive impairment in an AD mouse model." (PMID 34689137, 2021). "Besides, several studies showed that SYN2 knockout mice displayed obvious cognitive impairment." (PMID 29204248, 2017).
depression (3 papers, 2016 to 2022). "Rg1 (20 mg/kg) ameliorated memory impairment and depression-like behavior via downregulation of complexin-2 (CPLX2), synaptosomal-associated protein 25 (SNP25) and synapsin-2 (SYN2) expression in the hippocampus of mice." (PMID 35953850, 2022). "Importantly, CPLX2, a depression- and memory-related protein, and SYN2 and SNP25, two memory-related proteins, were significantly downregulated in the hippocampus of 3xTg-AD mice, while the expression of these proteins was significantly modulated by the treatment of Rg1 treatment." (PMID 29204248, 2017).
memory impairment (3 papers, 2017 to 2022). "Rg1 can improve memory impairment and depression-like behavior in 3 × Tg-AD mice by upregulating the expression of the depression and memory-related proteins complexin-2 (CPLX2), synapsin-2 (SYN2), and synaptosomal-associated protein 25 (SNP25)." (PMID 34149431, 2021). "Thus, it is suggested that Rg1 may exert the protective effects against memory impairment via upregulating the expression of SYN2 in the hippocampus of 3xTg-AD mice." (PMID 29204248, 2017).
breast carcinoma (2 papers, 2014 to 2024). "SYN2 encodes a neuronal phosphoprotein (Synapsin 2) and is deregulated in human glioblastoma multiforme and breast cancer." (PMID 24886479, 2014). "In addition, there have been reported that the expression level of SYN2 is significantly related to the prognosis of breast cancer, suggesting that it may play a role." (PMID 39749343, 2024).
glioblastoma (2 papers, 2014 to 2023). The most malignant astrocytic tumor (WHO grade IV). "In human glioblastoma multiforme, SYN2 and TIMP4, a metalloproteinase-encoding gene located within an intron of SYN2, are subjects to reciprocal deregulation." (PMID 24886479, 2014). "SYN2 has been previously associated with glioblastoma and prostate cancer, but little evidence is available to date to support a role of SYN2 in CRC." (PMID 37640106, 2023).
mood disorder (2 papers, 2016). A cognitive disorder a disturbance in which the person's mood is hypothesized to be the main underlying feature. "Synapsin genes – Synapsin I (SYN1), Synapsin II (SYN2), and Synapsin III (SYN3) – are interesting candidates for the etiology of mood disorders due to their involvement in the adult brain in synaptic transmission and plasticity, as well as in brain development in axon outgrowth and synaptogenesis." (PMID 27515700, 2016).
neuroblastoma (2 papers, 2012 to 2022). Neuroblastoma (NB) is the most common solid, extracranial childhood tumor. "Expression of SYN2 is increased in human neuroblastoma cells treated with nicotine." (PMID 36544485, 2022).
Obesity (2 papers, 2022 to 2023). Accumulation of substantial excess body fat. "Abcg1, Aldoa, Mrap, Pex13, Aldh6a1, Egln3, G0s2 and Syn2 are significantly increased in adipose or liver tissue of ob/ob mice compared with lean mice, suggesting these genes are associated with obesity, are very rarely reported to be related to adipogenesis." (PMID 34974794, 2022). "We looked for common genes between the up-DPpGCs in TS and TA, and the significant differentially expressed genes (DEGs) induced by exercise in SkM of old mice, and found four genes, ATP1A3, SLC17A7, SYN2, and COL24A1 from the up-DPpGCs in TS, that are related to neurotransmission and obesity." (PMID 36769072, 2023).
Alzheimer disease (1 paper, 2022). A progressive, neurodegenerative disease characterized by loss of function and death of nerve cells in several areas of the brain leading to loss of cognitive function such as memory and language. "Previous studies show that synaptosomal-associated protein 25 (SNAP-25) and synapsin 2 (SYN2) genes associated with synaptic vesicle release, were among the most prominently downregulated differentially expressed genes in the prefrontal cortex of humans with Alzheimer’s disease (AD)." (PMID 36293516, 2022).
Atrophy (1 paper, 2022). Any weakening or degeneration, especially through lack of use. "More generally, genetic aberrations of many of the differentially methylated genes in our study, i.e., TRIO, NRXN2, SYN2, CACNA1E, DNM1 and RAB11B, have been associated with movement disorders, cognitive and visual impairments and brain abnormalities (e.g., atrophy, white matter apoplasia)." (PMID 35094644, 2022).
COVID-19 (1 paper, 2021). A disease caused by infection with severe acute respiratory syndrome coronavirus 2. "The comparison between COVID-19 patients showed that children with mild symptoms had higher mRNA concentrations of HERV genes than those with severe complications (significantly for all, but SYN1 and SYN2) or MIS-C (significantly for all, but borderline values for SYN1)." (PMID 34299101, 2021).
dementia (1 paper, 2008). Loss of intellectual abilities interfering with an individual's social and occupational functions. "Accordingly, down-regulation of synapsin II expression could interfere with normal nerve signal transmission and may contribute to the dementia and other changes in brain function associated with AD." (PMID 23584752, 2008). "Synapsin II, which was found to be downregulated in dementia patients, is involved in synaptic vesicle metabolism and neurotransmitter release." (PMID 23584752, 2008). "More detailed analyses demonstrated that synapsin II downregulation does not occur in all brain regions of dementia patients but is limited to those regions that are at greatest risk of developing the damage characteristic of AD." (PMID 23584752, 2008).